INS (insulin)
Diseases named in the same sentence as INS in open-access papers (continued):
Sharing a sentence is not in itself a finding about the gene and the disease.
diabetes (continued). "Currently, available treatments for diabetes encompass insulin injections and oral hypoglycemic agents." (PMID 39698026, 2023). "In REVITA-2 trial, there were also some differences in baseline insulin concentrations, numbers of medications, and disease duration of diabetes between the European and Brazilian cohorts, which also resulted in the regional differences in subgroup outcomes." (PMID 37800801, 2023). "Diabetes develops when the normal interplay between insulin secretion and the insulin sensitivity of target tissues is disrupted." (PMID 37409234, 2023). "This inflammatory environment damages t β-pancreatic cells, responsible for insulin production, exacerbating the development of diabetes." (PMID 37701031, 2023). "Little is known about complete remission in Type 1 diabetes mellitus (T1D) with the discontinuance of insulin treatment for a period of time." (PMID 37100887, 2023). "Renal clinic attendees with insulin-treated T2DM had a higher burden of diabetes-related complications including diabetic foot disease, retinopathy, hypoglycaemia, and hospitalisation." (PMID 37152098, 2023). "Diabetes mellitus is a lifelong metabolic disease characterized by chronic hyperglycaemia due to a combination of abnormal insulin secretion and/or defective insulin utilization and multiple factors." (PMID 37620853, 2023). "Type 2 diabetes, also known as non-insulin-dependent diabetes mellitus, is the predominant manifestation of the condition, including approximately 90%–95% of cases characterized by insufficient insulin production or utilization." (PMID 37954853, 2023). "The DiaTrend dataset is composed of intensive longitudinal data from wearable medical devices, including a total of 27,561 days of continuous glucose monitor data and 8,220 days of insulin pump data from 54 patients with diabetes." (PMID 37612336, 2023). "This is closely followed by HbA1c approach (85.7%), followed by duration of diabetes (74.7%), age (71.1%), insulin use (70.5%), and baseline grade alone (68.2%)." (PMID 38079169, 2023). "In patients with severe diabetes, as indicated by the need for insulin preoperatively, better glycemic control and higher remission rates were seen with shorter common channel lengths in duodenal switch." (PMID 37816973, 2023). "Insulin resistance can be evident long before the development of diabetes and thus elevated fasting levels of insulin can potentially predict the onset of this metabolic disorder." (PMID 37504117, 2023). "One participant who dropped out of the study was hospitalised for ketoacidosis during the control period prior to making any diet or insulin changes." (PMID 37432920, 2023). "The convenience and reduced burden of diabetes management through wearable insulin biosensors can significantly enhance the quality of life for individuals with diabetes." (PMID 38239544, 2023). "For diabetes treatment, nine (6%) patients were prescribed diet and exercise only, 95 (62%) were taking oral hypoglycemic agents alone, 35 (23%) were taking insulin, and 22 (15%) were taking glucagon-like peptide-1 receptor agonists." (PMID 37993771, 2023). "In the last case, models were trained for insulin sensitivity, glycated hemoglobin A1c (HbA1c), age, sex, Body Mass Index (BMI), prediabetes, and the occurrence of diabetes, reaching an AUC at 87% for T2DM discernment and 68% for prediabetes." (PMID 37047748, 2023). "Diabetes mellitus (DM) is a metabolic disease characterized by hyperglycemia resulting from defects in insulin secretion and/or its action." (PMID 36901554, 2023). "The 2016 edition of the Chinese technical guidelines for the injection of diabetes drugs recommended the use of a needle-free syringe for insulin injection as one of the most used insulin injection devices in clinical practice." (PMID 37501783, 2023). "The DSC worked to support her around the changes implemented in the diabetes management plan, identify and support goals, and empower her around mealtime insulin boluses." (PMID 37535407, 2023).
diabetes (continued). "Not being a member of an immigrant group, having a family history of diabetes, and using insulin during pregnancy were the predictors of follow-up adherence." (PMID 37779767, 2023). "Qualitatively, they also identified barriers such as insufficient knowledge about diabetes technologies, access to financial coverage for diabetes technologies, and diabetes self-management skills (eg, insulin dose adjustments)." (PMID 37440296, 2023). "These actions suggest a potential for HDL-C to safeguard insulin secretion and avert the onset of diabetes mellitus." (PMID 38066772, 2023). "A study conducted by Eli Lilly® compared preferences between two reusable insulin pen devices in pen-naïve adults with diabetes mellitus type 1 (DM1) and type 2 (DM2) in the United States of America." (PMID 37005930, 2023). "Diabetes mellitus was once a fatal disease; nevertheless, the discovery of insulin in 1921 made it a treatable, chronic condition." (PMID 37965322, 2023). "In contrast, the release of inflammatory cytokines such as TNF-α and resistin is increased in obesity and diabetes, which also contributes to insulin resistance by interfering with the insulin signaling pathway." (PMID 37298274, 2023). "Islet β cells are also the target cells of insulin, and dysfunction of insulin signal transduction in β cells can lead to an impaired number and function of β cells, which is one of the important pathophysiological changes in diabetes." (PMID 36748222, 2023). "Diabetes mellitus is a metabolic disorder characterized by chronically elevated blood glucose levels due to defective insulin release or function." (PMID 38203642, 2023). "Drugs currently approved to treat type 2 diabetes mellitus (T2DM) mostly work by increasing insulin secretion or reducing glucose concentration but are unable to fully improve insulin sensitivity and protect beta-cells." (PMID 37072850, 2023). "The mean duration of DM was nearly 14 years among study groups (p = 0.396), and the distribution of diabetes treatment (insulin alone, oral antidiabetic alone, or insulin + oral antidiabetic) was similar (p = 0.349)." (PMID 36837465, 2023). "Due to these actions on insulin and glucose, suppression of glucagon action was initially considered a good strategy to treat diabetes." (PMID 36943057, 2023). "Most diabetes drugs can be continued during COVID-19, but insulin is often preferable in severe conditions." (PMID 37374918, 2023). "Like other studies, we found treatment of Type 2 diabetes mellitus in Canadian children consists predominantly of lifestyle counseling, metformin monotherapy or in combination with insulin." (PMID 40303241, 2023). "On the contrary, in the American Diabetes Association (ADA) guidelines, insulin is the preferred agent for the management of glycemic control during pregnancy." (PMID 37401946, 2023). "It has been shown that supplementation with magnesium enhances insulin sensitivity in patients with diabetes." (PMID 37764713, 2023). "Under this condition, which is a prominent feature of diabetes, β‐cells lose their ability to synthesize insulin and enter an apoptotic stage." (PMID 37568265, 2023). "HepG2 cells are a legitimate in vitro cell model of human hepatocytes in diabetes studies because of their preserved insulin downstream signaling pathways." (PMID 37158952, 2023). "There are approximately 40 different types of diabetes, with some common types being Type 1 (insulin-dependent), Type 2 (insulin-independent), gestational diabetes, and pre-diabetes." (PMID 37953921, 2023). "Future studies should also incorporate both controlled and uncontrolled diabetes, where insulin is administered to appropriately represent the diabetic population." (PMID 37169119, 2023). "Type 2 diabetes mellitus (T2DM) is a disease commonly attributed to pancreatic insufficiency, inadequate insulin secretion, or increased insulin resistance, and accounts for the majority of all diabetes cases worldwide." (PMID 37895057, 2023).
diabetes (continued). "Our results build upon their findings by evaluating the relationships between diabetes, blood glucose control, insulin exposure, and HCC in the presence of existing advanced chronic liver disease, which remains the primary risk factor for HCC." (PMID 38055642, 2023). "Our research question focused on adults with type 1 or 2 diabetes on insulin therapy: What diabetes app functions are helpful as explained by a theory on motivation, called the Self-Determination Theory (SDT), to promote self-management behaviors?" (PMID 36826987, 2023). "For instance, TRE lowers body weight, improves insulin sensitivity and lipid profile in mice, and alleviates diabetes-induced cognitive impairment by gut microbiota." (PMID 37488260, 2023). "Although abundant data is demonstrating that PTPN2 alleviates insulin resistance in diabetic mice, some studies have shown a conflicting result that activation of PTPN2 inhibits insulin signaling, thereby exacerbating the development of diabetes." (PMID 37670950, 2023). "For some people with insulin‐treated diabetes and anti‐insulin antibody‐mediated dysglycaemia, antibody depletion therapy has been demonstrated to have clinical benefit." (PMID 37562398, 2023). "In the United Kingdom (UK), the average duration of diabetes is 8.5 years with hyperglycaemia (HbA1c 84 mmol/mol) before insulin is first prescribed, suggesting a significant, up to 5 years delay, which brings forward the risk of diabetes complications." (PMID 37237318, 2023). "With the increase in diabetes prevalence and mitochondrial toxicity, it is therefore imperative to understand how mitochondrial toxicological agents can potentially compromise insulin sensitivity." (PMID 36860368, 2023). "The duration of insulin use for type 1 diabetes and diabetes of the other type were 11.4 ± 6.7 years, and 4.92 ± 5.4 years, respectively." (PMID 37474582, 2023). "The primary culprits behind diabetes are either insufficient insulin production, impaired insulin function, or a combination of both." (PMID 38111407, 2023). "Some mutations in the insulin gene can lead to specific subtypes of diabetes, such as mutant INS gene–induced diabetes of youth (MIDY), maturity onset diabetes of the young (MODY), or neonatal diabetes." (PMID 36983642, 2023). "In patients with diabetes mellitus, advanced age, duration of the disease, insulin use, presence of coronary artery disease, and elevated serum creatinine are all independent risk factors for the development of heart failure (HF)." (PMID 37954809, 2023). "Ninety percent of diabetes cases are type 2 diabetes mellitus (T2DM), which is typified by people with postprandial hyperglycemia linked to either poor insulin secretion, resistance to insulin, or both." (PMID 38201083, 2023). "For the same reason, the expression of HK2 is decreased in type 1 diabetes mellitus (T1DM) due to reduced insulin signaling and is recovered upon insulin treatment in T1DM." (PMID 37109475, 2023). "Yet diabetes medications such as metformin and thiazolidinediones, or TZDs, are insulin sensitizers that lower blood glucose, at least in part, by reducing IR." (PMID 37372966, 2023). "This adipokine can also improve the diabetes of lipodystrophic mice independently of insulin, suggesting that leptin has therapeutic potential for the treatment of T1DM." (PMID 36674935, 2023). "The elevated insulin signaling in adipose tissues is involved in suppressing the progression of type 2 diabetes mellitus." (PMID 36902049, 2023). "Chronic ingestion of a high-fat high-carbohydrate diet has been shown to compromise the sensitivity of peripheral tissues to insulin, resulting in hyperglycaemia, prediabetes or diabetes." (PMID 38096150, 2023). "Diabetes mellitus (DM) is an array of metabolic diseases with clinical features of hyperglycemic conditions that arise due to impairment in insulin action, secretion, or the two." (PMID 37958788, 2023).
diabetes (continued). "We also assessed their impression of the potential of connection-enabled insulin devices to facilitate their diabetes care." (PMID 36828942, 2023). "Current management for diabetes has stimulated the development of versatile 3D-based hydrogels as in vitro platforms for insulin release and as support for the encapsulation of pancreatic cells and islets of Langerhans." (PMID 37298999, 2023). "Inspection of the same counts among the diabetes‐treated groups, however, indicates that the fold increase of insulin+ cells is higher than the fold increase of glucagon+ cells." (PMID 36647783, 2023). "Among Asian patients with diabetes, especially in China, there is a greater fear of injections and more incredible difficulties in using insulin than Western patients." (PMID 37654567, 2023). "The UKPDS data from large studies shows that at the time patients are diagnosed with diabetes, nearly half of the function of secreting insulin has been lost, and the function of islet B cells in relation to the vitamin D diminished progressively." (PMID 37046484, 2023). "Beta cells couple stimulation by glucose with insulin secretion and impairments in this coupling play a central role in diabetes mellitus." (PMID 37701894, 2023). "The strategy of using the assembly of NG as a coating achieves the oral delivery of insulin and showcases a potential for the treatment of diabetes." (PMID 37587777, 2023). "The DCCT study demonstrated the value of insulin pump therapy in maintaining glycaemic control and preventing microvascular complications in children and adults with diabetes." (PMID 37185052, 2023). "Although oral treatment of diabetes has made significant progress in achieving convenience and effectiveness, different insulin-based agents still face great challenges in toxicology, poor stability, and individual variability in absorption." (PMID 37514488, 2023). "Insulin resistance and defects in insulin secretion are quite evident in type 2 DM, which accounts for approximately 90-95% of all cases of diabetes." (PMID 37868554, 2023). "Prior to the discovery of insulin, type 1 diabetes mellitus was treated with very-low carbohydrate diets (VLCD) that kept daily carbohydrate intake below 10 g." (PMID 37584373, 2023). "We formulated a base model for the undisturbed glucose-insulin regulatory system, upon which, we built the diabetes progression model framework with a generalized diabetogenic factor." (PMID 36848379, 2023). "The extracellular transport of Aβ is accelerated by insulin, thus explaining why diabetics have a significantly increased incidence of AD." (PMID 38136211, 2023). "The effect of phosphorylation on diabetes occurs mainly through the cascade of kinases and phosphatases that regulate insulin signaling." (PMID 37143582, 2023). "The aggregation of insulin prevents rapid uptake of insulin by cells, which in the treatment of diabetes can lead to localized injectable amyloidosis, which provokes an undesirable immune response and tissue necrosis." (PMID 36835194, 2023). "Insulin is primarily responsible for glucose regulation; uncontrolled hepatic glucose production and hyperglycemia are metabolic diseases due to the abnormal insulin production in people with diabetes." (PMID 37241943, 2023). "One predictive factor for continuing to meet the ADA criteria for bariatric metabolic surgery after primary surgery is diabetes treatment that depends on insulin." (PMID 37587379, 2023). "SMBG has been a vital practice for optimizing diabetes therapy in individuals with diabetes, particularly those dependent on insulin therapy, such as individuals with T1DM and T2DM." (PMID 37637581, 2023). "Non-insulin-treated diabetes mellitus and obesity ranked third and fourth, respectively, affecting approximately 16% of the patients." (PMID 37476132, 2023).
diabetes (continued). "Until recently, treatment of childhood-onset Type 2 diabetes mellitus has been limited to metformin and insulin, however, new drugs approved for use in pediatric Type 2 diabetes mellitus such as glucagon-like peptide (GLP-1) agonists show promise." (PMID 40303241, 2023). "Intensive Insulin therapy was found to induce diabetes remission in nearly half of the patients at one year irrespective of body weight." (PMID 36829204, 2023). "The mean body mass index (BMI) was 27.5 kg/m2, and 26.3% of patients had diabetes mellitus, but only one patient was insulin dependent." (PMID 37368152, 2023). "In Viet Nam, 88% of respondents reported stocking blood glucose test strips, 65% reported stocking blood glucose meters, 82% reported stocking OAM, and 40% reported stocking insulin; 30% of respondents reported stocking all four types of diabetes products." (PMID 37386440, 2023). "Diabetes mellitus (DM) is characterized by hyperglycemia that results from decreased tissue response to insulin and/or inadequate insulin secretion in the complex pathways of hormone action." (PMID 36839851, 2023). "Dpy30-KO mice developed impaired glucose tolerance and had reduced serum insulin levels by 45 days post tamoxifen administration and then rapidly developed diabetes, prompting euthanasia by 60 days." (PMID 36912927, 2023). "Cash prices for diabetes medications in the US can vary considerably and that the greatest degree of price variation occurs in non-insulin generic therapies." (PMID 38060500, 2023). "She had been diabetic since her last delivery and had medicines for diabetes mellitus including insulin, hypertension and dyslipidemia.I mainly take these three tablets (for TB)." (PMID 37658369, 2023). "There have been rapid advancements in diabetes technology since the discovery of insulin a century ago." (PMID 37289734, 2023). "88.4% of active subscribers (n = 938) had a diagnosis of Type 1 Diabetes Mellitus or equivalent inscribed on their emblem, and 84.2% (n = 893) stated use of insulin." (PMID 36334194, 2023). "Type 1 Diabetes Mellitus (T1DM) is a common hyperglycemic disease characterized by the autoimmune destruction of insulin-producing beta cells of the pancreas." (PMID 36983604, 2023). "Higher glucose levels and abnormalities in insulin production or action commonly describe diabetes mellitus (DM)." (PMID 38202711, 2023). "Diabetes mellitus: Patients on oral hypoglycemic agents (OHAs) or insulin or having a fasting plasma glucose level above 126 mg/dl are considered as having diabetes mellitus." (PMID 37342754, 2023). "Quercetin can act on several therapeutic targets in diabetes, including inhibiting intestinal glucose absorption, improving insulin secretion, enhancing insulin action, improving glucose utilization in peripheral tissues." (PMID 37868908, 2023). "While there are studies that describe a positive effect of HMB supplementation on glycemic control and other parameters related to diabetes, other studies have described conflicting effects on insulin sensitivity." (PMID 38004100, 2023). "8.8% of T2D participants with only microvascular complications were treated with insulin, and 74.8% with oral diabetes medication." (PMID 37644580, 2023). "The PID controller acts as a physician analyzing the glucose level of a patient with diabetes; if the glucose level goes up, the insulin dosage should increase proportionally, and the opposite would happen if the glucose level decreases." (PMID 37256680, 2023). "We analysed the rates of decline in both glucose and insulin sensitivity from study entry to year −1 and from year −1 to diabetes onset." (PMID 36459177, 2023). "Diabetes is a chronic metabolic disease characterized by hyperglycemia due to a reduction in the production and/or action of insulin." (PMID 36946851, 2023).